CHRNB4 (cholinergic receptor nicotinic beta 4 subunit)
Diseases named in the same sentence as CHRNB4 in open-access papers (continued):
Sharing a sentence is not in itself a finding about the gene and the disease.
myopia (1 paper, 2025). "This study employs a guinea pig myopia model to investigate the effects of bilberry extract combined with DHA on Chrnb4 expression and its functional implications in scleral remodeling." (PMID 40534703, 2025). "In the context of eye health and myopia, research has indicated that the Chrnb4 gene is highly expressed in neural and ocular tissues." (PMID 40534703, 2025). "Further research is needed to elucidate the precise pathways and interactions involving Chrnb4 in the development and progression of myopia." (PMID 40534703, 2025). "This study investigated the combined effect of bilberry extract and docosahexaenoic acid (DHA) on the expression of the Chrnb4 gene in the sclera of guinea pigs with lens-induced myopia (LIM)." (PMID 40534703, 2025). "It is believed that Chrnb4 may influence the development of myopia by regulating the remodeling of the extracellular matrix (ECM) and the activity of scleral fibroblasts." (PMID 40534703, 2025). "By analyzing Chrnb4 expression levels under varying intervention conditions and their correlation with scleral structural changes, this research aims to uncover the mechanistic basis of these natural compounds in myopia management." (PMID 40534703, 2025). "Light adaptation integration: Chrnb4-mediated cholinergic signaling enhances photic adaptation through the retinal ON pathway, indirectly sustaining rhythmic dopamine secretion to counteract myopia progression." (PMID 40534703, 2025). "The combination of bilberry extract and DHA demonstrates significant efficacy in controlling myopia progression through multiple mechanisms, including upregulation of Chrnb4 gene expression, modulation of the TGF-β/MMP-2/TIMP-1 signaling pathway, and enhancement of dopamine levels." (PMID 40534703, 2025). "While the exact mechanisms through which Chrnb4 influences myopia are still being explored, its role in modulating the ECM and scleral fibroblast activity suggests that it could be a significant factor in the pathogenesis of this condition." (PMID 40534703, 2025). "Chrnb4 expression, which is involved in scleral remodeling and may affect myopia development, was significantly upregulated in the combined treatment groups (Model+DHA+Bilberry) compared to the model group." (PMID 40534703, 2025). "This suggests that Chrnb4 plays an important role in the protective effects of DHA and bilberry extract, possibly by influencing extracellular matrix (ECM) remodeling in the sclera, which is a key factor in axial elongation during myopia development." (PMID 40534703, 2025). "Emerging evidence suggests that Chrnb4 may regulate ECM remodeling and scleral fibroblast activity, thereby influencing myopia development." (PMID 40534703, 2025).
psychosis (1 paper, 2025). "Among the 170 propsychotic target genes, 8 were a high-confidence psychosis risk gene (GRIN2A, DRD2, CYP2D6, CHRNB4, CHRM4, GABBR1, GRM3, CHRNA3)." (PMID 40701976, 2025).
squamous cell carcinoma (1 paper, 2020). A carcinoma arising from squamous epithelial cells. "Therefore, we believe that here we provide evidence for the high expression of CHRNB4 caused by tobacco and alcohol, thereby inducing the formation of squamous cell carcinoma through cancer-related pathways such as mTOR." (PMID 33304845, 2020). "Consistent results showed that CHRNB4 was upregulated and more frequent in squamous cell carcinoma than in LUAD." (PMID 33304845, 2020). "The specific expression analysis revealed that CHRNB4 is highly expressed selectively in squamous cell carcinomas compared to adenocarcinoma." (PMID 33304845, 2020).
type 2 diabetes (1 paper, 2023). "This notion is further supported by the presence of type 2 diabetes susceptibility signals intersecting eQTLs for the ADRA2A, CHRNB4 and P2RY1 genes." (PMID 36897571, 2023).
tumor (10 papers, 2010 to 2026). "Re-expression of CHRNB4 in resistant cells, a primary gain-of-function approach, significantly impaired colony formation, and tumor growth in vivo." (PMID 42073514, 2026). "The MHCF1 unique mutations consisted of protein misfolding (Hsp-related genes) and acetylcholine receptor (Chrnb4 and Chrm5) genes that possibly act on cancer cell processes, and tumor suppressor (Adamts1 and Adamts5) and cell cycle (Aurkb and Bub1) genes." (PMID 34158541, 2021). "Our study suggests the potential of CHRNB4 as a target for direct regulation of HNSC tumor cells and the potential of NTRK1 as a target for regulation of mast cells." (PMID 34912722, 2021). "Single-cell sequencing data of HNSC showed that CHRNB4 was mainly expressed in tumor cells, and multiple metabolic pathways were enriched in high CHRNB4 expression tumor cells." (PMID 34912722, 2021). "The most consistent overall DNA methylation difference between tumor and adjacent normal tissue on 15q25 was tumor hypomethylation in the promoter region of CHRNB4, which resulted in overexpression of the transcript in tumors." (PMID 29416783, 2018). "Consistently, some researchers have studied the diagnostic and prognostic value of partial CHRNs (only 8 genes) in ESCC and found that CHRNB4 expression was higher in tumor samples than in both the matched surrounding mucosa and esophagus samples from healthy individuals." (PMID 33304845, 2020). "Cox proportional hazards regression analysis was performed to find that just the single gene CHRNB4 has enough independent prognostic ability, with the area under curve surpassing the tumor-node-metastasis (TNM) staging-based model, the most commonly used model in clinical application in ESCC." (PMID 33304845, 2020). "In addition to this, the normal region in adjacent tumour tissue also showed very low CHRNB4 expression (green arrowed)." (PMID 32455963, 2020). "In our study, we identified three upregulated genes (CHRNB4, CHRNA6, and CHRNA9) of the whole CHRNs between tumor tissues and normal controls in three kinds of SCCs." (PMID 33304845, 2020). "This suggests that CHRNB4 may promote tumor development by directly affecting tumor cells, and NTRK1 may change the tumor microenvironment by affecting mast cells." (PMID 34912722, 2021). "CHRNA5, CHRNA10, CHRNB4, CHRND, CHRNE, and CHRNG, however, were not expressed at levels significantly different from the non-tumor control samples." (PMID 31590360, 2019). "Scaled expression levels across the remaining nine candidate ECs analysed indicated within-gene differences in expression between tumour and normal tissue groups in both SLC25A23 (p = 0.040) and CHRNB4 (P = 0.002) but not in the remaining genes (p > 0.05)." (PMID 20122155, 2010).
cancer (9 papers, 2015 to 2024). A tumor composed of atypical neoplastic, often pleomorphic cells that invade other tissues. "Gene Set Enrichment Analysis results suggested that the expression of CHRNB4 was associated with cancer-related pathways, such as the mTOR pathway." (PMID 33304845, 2020). "For β4 nAChR, most studies have focused on the CHRNA5/CHRNA3/CHRNB4 cluster, wherein polymorphisms may be associated with an increased risk of death and incidence of cancer among smokers." (PMID 36284268, 2022). "Still, our comprehensive bioinformatics analysis of cancer–nerve crosstalk-associated genes in SKCM constructed a valuable prognostic model based on eight genes (GRIN3A, CCR2, CHRNA4, CSF1, NTN1, ADRB1, CHRNB4, and CHRNG) and common clinical characteristics." (PMID 37404751, 2023). "Based on the single-cell sequencing data of HNSC, we found that CHRNB4 was mainly expressed in cancer cells, while NTRK1 was mainly expressed in mast cells." (PMID 34912722, 2021). "The number of cancer-related genes co-expressed with CHRNB4 in the CHRNB4-high group was found to be more than that of the CHRNB4-low group, with odds ratios of 4.71 for ACSN and 1.71 for DisGeNET." (PMID 32455963, 2020). "Because CHRNB4 seems to be a very critical gene according to the expression and survival analysis, we then explored its expression specificity in different cancer types." (PMID 33304845, 2020). "On the basis of the results of the CHRNB4 gene editing and drug inhibition assay, we considered varenicline to be a potential targeted drug that may reduce cancer metastasis in smoking HNSCC patients who have high CHRNB4 expression." (PMID 32455963, 2020). "In the present study, integration of the analysis of gene expression, overall survival, cancer-related pathways, and the experiments of CHRNB4 gene editing and drug treatment suggested that CHRNB4 is a promising prognostic biomarker and drug target for smoking HNSCC patients." (PMID 32455963, 2020). "CHRNB4 was also associated with long noncoding RNA, such as DHRS4-AS1, DHRS4L2, DHRS4L1, and SMAD5-AS1, which functions by affecting the proliferation, invasion (epithelial-mesenchymal transition), cell cycle progression and the apoptosis of cancer cells." (PMID 33304845, 2020). "Besides, the Venn diagram demonstrated that there were three mutual DEGs in all three cancers: CHRNB4, CHRNA9, and CHRNA6." (PMID 33304845, 2020). "We found the expression of CHRNB4 was higher in cancer with SCCs including CECC, LUSC, HNSC, and ESCC than in adenocarcinomas (AC) such as STAD, LUAD, PAAD, COAD, READ, and EAC, suggesting that CHRNB4 was significantly and specifically upregulated in SCCs compared to ACs." (PMID 33304845, 2020). "We reconstructed a simplified network as the reference template to illustrate signalling interactions among the common and different pathways regulated by smoking patients with CHRNB4-high expression and CHRNB4-low expression according to “pathways in cancer” (KEGG: hsa05200)." (PMID 32455963, 2020). "In cell proliferation experiment, we also found that knockdown of CHRNB4 by siRNA dramatically restrained the proliferation in ESCC cells, suggesting that CHRNB4 may significantly and independently affect the patient’s survival by changing the proliferation rate of cancer cells." (PMID 33304845, 2020). "On the other hand, the telomere length-associated gene TERC and oxidative stress response gene NFE2L2 were more frequently amplified in the CHRNB4-high subgroup, which could immortalize cells and against oxidative stress for promoting cancer cell survival and escaping apoptosis." (PMID 32455963, 2020). "To understand the association of tumorigenesis and poor prognosis with high CHRNB4 expression, we first collected 93 pathways with 2652 genes involved in cancer hallmarks from the Atlas of Cancer Signalling Network (ACSN) database and 3530 cancer-related genes from the DisGeNET database." (PMID 32455963, 2020).
cancer (continued). "In the CHRNB4-high subgroup, CHRNB4 was co-expressed with numerous genes, such as ADCY9, NOTCH3, ARNT, NCOA1, and NCOA3, which correlated with multiple cancer-related processes, but only one gene, FLT4, was co-expressed in the CHRNB4-low subgroup." (PMID 32455963, 2020).
adenocarcinoma (2 papers, 2018 to 2020). A common cancer characterized by the presence of malignant glandular cells. "The enrichment was stronger and more extensive in the squamous cell type, which had three loci associated with SCZ, and only one with adenocarcinoma (the CHRNA3/CHRNA5/CHRNB4 cluster on chromosome 15q25.1)." (PMID 29330379, 2018).
diseases of the central nervous system (1 paper, 2025). "These include genes involved in neurodegeneration (EIF5), diseases of the central nervous system (IPO13, ST3GAL3), tobacco addiction (CHRNB4, PSMA4), fatty acid metabolism (ACSBG1), and skin conditions (HYI, ELOVL1)." (PMID 40074595, 2025).
CHRNB4 also shares sentences with these, for which no sentence is quoted: chronic obstructive pulmonary disease (3 papers); acute myeloid leukemia (1); Alcoholism (1); Alzheimer disease (1); bipolar disorder (1); brain disorder (1); cardiovascular disease (1); cocaine dependence (1); colorectal tumours (1); emphysema (1); frontotemporal dementia (1); head and neck cancer (1); Hypertension (1); neuroblastoma (1); non-small cell lung carcinoma (1); Obesity (1); parasite infection (1); peripheral artery disease (1); specific language impairment (1).